EGFR (epidermal growth factor receptor)
Diseases named in the same sentence as EGFR in open-access papers (continued):
Sharing a sentence is not in itself a finding about the gene and the disease.
tumor (continued). "Consequently, we selected two human tumor cell lines having high to intermedium EGFR expression levels, A431 that express 2–3 × 106 EGFR molecules per cell and H125 that express 2.1 × 105 EGFR molecules per cell." (PMID 29056908, 2017). "EGFR activation promotes tumor cell proliferation, angiogenesis, invasion, and metastasis." (PMID 28039459, 2017). "The leucine-rich repeats and immunoglobulin-like protein 1 (LRIG1), which is a negative regulator of EGFR, are tumor suppressors that inhibit receptor tyrosine kinases and may be related to chemoresistance." (PMID 29230082, 2017). "Interestingly, fusing the scFv anti-EGFR to single-chain TRAIL (scTRAIL), instead of a single monomer of TRAIL, further increased the tumor killing efficiency of the scFv-TRAIL variant by 10-fold, highlighting the importance of TRAIL valency for its efficacy." (PMID 31548531, 2017). "Overall these findings support the view that EGFR contributes to immune escape not only by downregulating tumor cell immunogenicity (signal 1) or providing aberrant signals 2 and 3 but also inducing an acidic, lactate rich milieu that impairs an effective adaptive antitumor immunity." (PMID 28611673, 2017). "Moreover, gefitinib-mediated inhibition of EGFR destabilized PD-L1 surface expression in a GSK3β dependent fashion and enhanced tumor specific T cell immunity measured by CD8+ T cell IFNγ and granzyme B production." (PMID 28611673, 2017). "Although response rates were higher in patients with EGFR mutant tumours, the use of erlotinib in molecularly unselected NSCLC patients after failure of one or two lines of chemotherapy demonstrated modest survival and quality of life benefit compared to placebo in all patients." (PMID 29050231, 2017). "Finally, we present evidence that REP1 knockdown inhibits growth of human tumor xenografts in mice, with downregulation of EGFR." (PMID 28230863, 2017). "Moreover, tivozanib synergistically enhanced anti-tumour effects of EGFR-directed therapies including erlotinib." (PMID 28383032, 2017). "Localization and dynamics of EGFR-GFP in HSC3/EGFR-GFP tumor xenografts." (PMID 29268862, 2017). "Tumor tissue is still the recommended source for EGFR testing." (PMID 28061461, 2017). "Although LOX has previously been linked to SRC8, its role in EGFR signalling has not been reported, but like LOX, EGFR is implicated in both tumour cell growth and metastasis." (PMID 28416796, 2017). "This update is applicable to all European Union member countries and will benefit patients who have locally advanced or metastatic NSCLC without available or evaluable tumor samples for EGFR mutation analysis." (PMID 28099915, 2017). "Of note, EGFR amplification usually remains unchanged at the time of tumor recurrence." (PMID 29075855, 2017). "In this series, cytological tumour sampling was not the predominant reason why cancers failed to have EGFR mutation status established." (PMID 28367333, 2017). "EGFR-TKIs such as gefitinib, erlotiniband afatinibare currently used in the clinical treatment of cancer and compared to standard chemotherapy treatments, first-line treatment with EGFR-TKIs induces favorable anti-tumor responses." (PMID 28915593, 2017). "Therefore, it is warranted to have well designed large scale studies of patients and to design experiments on tumor cells to determine the precise mechanism(s) of the relationship between microRNA change and EGFR expression in plasma after EGFR-TKI treatment." (PMID 28496005, 2017). "Also, various predictors in the domains of serum markers, tumor and treatment characteristics have been included, but apart from EGFR in one DSS, biological markers for targeted and immunotherapies are still lacking." (PMID 28969629, 2017). "Collectively, our data demonstrated that combination of ABT-737 and erlotinib could induces tumor cells apoptosis, and shrinking the xenografts tumors produced by NSCLC cells expressing EGFR-mutant and harboring the BIM deletion polymorphism." (PMID 29312548, 2017).
tumor (continued). "Despite the heterogeneity of the sample, pooled results suggest that KRAS mutations act as a negative predictive marker for tumor response in NSCLC patients treated with anti-EGFR therapies." (PMID 29285236, 2017). "Importantly, pY1068/EGFR ratio values measured in human HNSCC specimens were within the range of those values found in mouse tumor xenografts of HSC3/EGFR-GFP cells, suggesting the presence of low EGFR ligand concentrations in human HNSCC." (PMID 29268862, 2017). "What are the mechanisms of EGFR endocytic trafficking in vivo in tumor cells?" (PMID 29268862, 2017). "However, in response to IR, some tumor cells activate DSBs repair and pro-survival pathways such as EGFR/ATM/ATR/BRCA1/Chk1 and PI3K/Akt or RAS/Raf/ERK1/2, rendering them radio-resistant." (PMID 28423495, 2017). "In contrast, the two patients with BRAFD594G-mutated tumours in our study did not achieve objective response to anti-EGFR antibody treatment." (PMID 28972961, 2017). "Interestingly, CNS disorders including ischemia, tumor development, and neurodegenerative diseases can re-upregulate EGFR in astrocytes, in a response termed reactive astrogliosis." (PMID 28513565, 2017). "p.T790M shows a complex biological behaviour, since p.T790M status in patients may change both temporally and spatially among tumor sites at least in part due to the selective pressure from EGFR-TKI." (PMID 29156777, 2017). "This may include the amount and timing of prior chemotherapy, including the use of anti-EGFR monoclonal antibodies, all of which may potentially radio-sensitise tumours." (PMID 28536968, 2017). "Twelve patients were detected to be EGFR mutation positive in tumor tissues but negative in plasma samples." (PMID 28829813, 2017). "The usefulness of residual tumor resection after epidermal growth factor receptor tyrosine kinase inhibitor (EGFR-TKI) treatment remains unclear." (PMID 29169381, 2017). "In addition, two other targets frequently found expressed in GCT tumor tissues are the glycoprotein of the extracellular matrix tenascin C (TNC) and the Epidermal Growth Factor Receptor (EGFR), described associated with GCT tumor progression." (PMID 28968976, 2017). "Additionally, correlations of ASP with histopathology and with the expression of the tumor proliferation markers KI-67 and epidermal growth factor receptor (EGFR) in NSCLC were found." (PMID 29058157, 2017). "Other CT features such as tumor size, cavitation, air-bronchogram, lobulation and spiculation did not demonstrate statistically significant correlation with EGFR mutations individually (P = 0.91; 0.67; 0.12; 0.45; and 0.36, respectively)." (PMID 28068946, 2017). "Amongst several tumor heterogeneity metrics included in our analysis, inverse coefficient of variation (1/COV) was a predictive factor (p < 0.02) of EGFR mutations status, independent of metabolic tumor diameter." (PMID 28881771, 2017). "Total EGFR immunostaining was also examined as a tumor marker." (PMID 28388009, 2017). "Lower levels of EGFR in these cells may be considered as an additional reason for the delayed tumor growth of the PHD2 knockdown cells in the xenograft assay." (PMID 28038470, 2017). "Further studies will be needed to determine the mechanism through which EGFR-PPARGC1A in cSCC regulate tumor formation, which may lead to a better understanding of the pathogenesis of cSCC, new diagnostic methods, and new targeted cancer therapies." (PMID 28978917, 2017). "Anti-EGFR-GN+NIR-PTT resulted in almost complete tumor regression." (PMID 29156817, 2017). "Furthermore, recent research indicate that nickel induce miR-21 via activation of the EGFR/NF-κB pathway and consequently promote tumor invasion." (PMID 29127306, 2017).
tumor (continued). "In particular, African women exhibit molecular profiles in their tumor closer to those of Asian than Caucasian women, and they could dramatically benefit from anti-EGFR and anti-ERBB2 targeted therapies." (PMID 28881604, 2017). "Microvesicles from A549 tumor cells contained a high level of EGFR and could transfer EGFR to endothelial cells." (PMID 29137230, 2017). "Several investigators have assessed circulating tumor DNA (ctDNA) in the blood of mCRC patients during anti-EGFR therapy and found that undetectable low-frequency KRAS-mutant clones may be selected by anti-EGFR treatment." (PMID 28368335, 2017). "Indeed, combination of radiotherapy and EGFR inhibitors can improve local tumor control compared to irradiation alone and this strategy has been introduced into clinical radiotherapy practice." (PMID 29160417, 2017). "Therefore, although tumor tissue should be the first sample choice for EGFR testing at diagnosis, ctDNA is a promising alternative diagnostic approach." (PMID 27980215, 2017). "This could partially be justified by the capacity of this mAb to mainly direct at the tumor, in which the EGFR expression is higher than in normal epithelial cells." (PMID 28674498, 2017). "In a recent study, it has been found that it is possible to engage and therefore redirect these T-cells to react to specific antigens (in this case EGFR which is often overexpressed on tumor cells) in order to redirect the anti-viral response into an anti-tumor response." (PMID 28944214, 2017). "However, no clear association has been found between the expression level of the EGFR protein in the tumours, determined by the FDA approved EGFR PharmDxTM kit, or other standard anti-EGFR antibodies, and the response to the EGFR inhibitors." (PMID 28032593, 2017). "The epidermal growth factor receptor (EGFR) is an important anti-tumor target." (PMID 28181832, 2017). "There are various ways to achieve this, for example, covering the viral surface with polymer to “cloak” the existing receptor and addition of epidermal growth factor (EGF) to target the virus to tumor cells which tend to have upregulated EGF receptor (EGFR) expression." (PMID 28944214, 2017). "Here we have achieved for the first time targeted lipopolyplex delivery of an imaging biosensor that can monitor EGFR activity in situ, in an attempt to provide a more accurate readout of the sensitivity of tumour cells to EGFR inhibition with tyrosine kinase inhibitors (TKI) in vivo." (PMID 28166195, 2017). "Patients who are tumor-tissue EGFR M- but cfDNA EGFR M+ have been described in many studies." (PMID 28052016, 2017). "For OSCC patients who are unable to provide lymph node or recurrent tumor samples for EGFR gene copy number analysis, examining primary tumors could provide EGFR clonal information in metastatic, recurrent or SPT lesions." (PMID 28854970, 2017). "Different from research exploring the mechanism of tumor transplantation and blood metastases as the object of study, this study primarily compared the efficacy of EGFR-TKIs in the treatment of intracranial tumors, for which the direct intracranial transplant method created a more consistent model." (PMID 29228726, 2017). "Here, we show that EGF up-regulates CCR1 expression, suggesting that CCR1 may contribute to EGFR-mediated tumor invasion and metastasis." (PMID 29212252, 2017). "For example, fragment length analysis can detect insertions and deletions but not point mutations in EGFR; pyrosequencing requires the proportion of tumor cells in a sample to be 20% or more to maintain its accuracy." (PMID 28938658, 2017). "While for those detected without EGFR mutations in cfDNA, further detection in tumor tissue is recommended." (PMID 28572536, 2017).
tumor (continued). "We detected epidermal growth factor receptor with MS/MS fragmentation data in a microdissected triple negative tumor section, with 29 unique peptides, corresponding to 33% sequence coverage and an estimated abundance that was among the top ten most abundant proteins detected in malignant cells." (PMID 28058811, 2017). "As such, while we showed that RCRC commonly demonstrates a genomic profile associated with resistance to anti-EGFR therapy, we propose future analyses should focus on individual tumors rather than primary tumor sidedness to best facilitate precision medicine." (PMID 29212173, 2017). "One potential mechanism by which the p38 pathway may exert its tumor suppressive role is promoting internalization and degradation of the ligand bound EGFR." (PMID 28410196, 2017). "EGFR amplification was also seen in tumours GB176 and GB182." (PMID 28655341, 2017). "This review will discuss evidence that implicates the involvement of the immune system in EGFR antagonist-based tumor treatment, considering the measures required to improve current treatment in order to enhance clinical efficacy and diminish any associated side effects." (PMID 28970798, 2017). "In the present work, we show that, consistently with previous data obtained with biotinylated anti-EGFR antibodies, AvidinOX anchorage significantly enhances in vitro anti-tumor activity of biotinylated anti-ErbB2 antibodies Trastuzumab (bTrast) or Pertuzumab (bPert)." (PMID 28186982, 2017). "Thus, we analyzed tumor cells growing on Matrigel monolayer for a possible co-localization between EGFR and integrin αvβ3." (PMID 28425453, 2017). "Treatment NSCLC harbouring mutant epidermal growth factor receptor (EGFR) with specific tyrosine kinase inhibitor (TKI) has led to remarkable tumor shrinkage and improvement in progression-free survival (PFS) and quality of life compared with standard chemotherapy." (PMID 28903458, 2017). "For instance, PET probes could not only be used for early detection of EGFR-positive tumor recurrence and stratification of cancer patients, but also for dose optimization of EGFR-TKIs therapy by monitoring the efficacy of EGFR-based tumor treatments." (PMID 28600491, 2017). "The authors studied the genotype of 22 genes (Ion Torrent, Ampliseq colon and lung panel), mainly involved in colorectal tumorigenesis, in primary tumor samples and liver metastasis from 7 KRAS-WT patients, both before and after chemotherapy associated to anti-EGFR." (PMID 29221448, 2017). "However, the capacity of nimotuzumab to kill EGFR + tumor cells by other effector mechanisms and to induce an innate and adaptive immune response had not been studied so far." (PMID 28674498, 2017). "Also, the interaction of EGFR signaling pathway and TKIs in both tumor cells and bone matrix cells was salient." (PMID 29113396, 2017). "Overall, this study suggests that EGFR signaling regulates global metabolic pathways in EGFR-mutated LAD cells and may be an important target to reverse tumor cell–derived metabolic immunosuppression." (PMID 28611673, 2017). "Therefore, it is crucial to identify the genotype of the tumor after the histopathological classification is determined to predict the sensitivity or resistance to an increasing number of EGFR-TKIs." (PMID 28496005, 2017). "In NSCLC, activation of the EGFR pathway plays a critical role in tumour development." (PMID 28771186, 2017). "For OSCC patients, in whom the lymph nodes or recurrence tumors were unavailable for EGFR gene copy number analysis, studies of the primary tumor could provide part of the EGFR clonal information to predict metastatic or recurrent lesions." (PMID 28854970, 2017). "Furthermore, REP1 knockdown effectively reduced tumor growth in a mouse xenograft model via EGFR downregulation and STAT3 inactivation in vivo." (PMID 28230863, 2017).
tumor (continued). "In addition to gene amplification, a mutant form of EGFR, generally known as EGFRvIII or ΔEGFR, occurs in about 50–60 percent of EGFR-overexpressing GMBs and is exclusively expressed in tumor cells." (PMID 28629170, 2017). "Thus, we show that LOX regulates EGFR cell surface retention to drive tumour progression, and we validate the therapeutic potential of inhibiting this pathway with the small molecule inhibitor CCT365623." (PMID 28416796, 2017). "One hypothesis of how this E-cadherin driven resistance mechanism may act, is that E-cadherin is shed from the tumor cells in a soluble form, which – as shown in in vitro model systems – may then activate EGFR promoting cell survival." (PMID 28199979, 2017). "In addition, administration of antiplatelet agent or podoplanin-neutralizing antibody suppressed the growth of LSCC tumour xenografts by inhibiting EGFR phosphorylation in vivo." (PMID 28642617, 2017). "The knowledge that EGFR inhibitor treatment may suppress the function of Tregs, thus aiding in improving the efficacy of tumor immunotherapy, allows the novel exploration of combination therapy." (PMID 28970798, 2017). "The PLA method also detected EGFR homodimerization in fixed tumor tissue from NSCLC patients." (PMID 29069773, 2017). "It indicated that tumor angiogenesis with abnormal perfusion and permeability may reflect the EGFR status." (PMID 29097933, 2017). "However, the intrinsic and acquired resistance to EGFR inhibitors in tumor cells has become a significant challenge in EGFR-targeted therapies." (PMID 28572590, 2017). "Then, CL4 was detected on stable tumor derived cell lines that express high levels of EGFR." (PMID 28635657, 2017). "Icotinib was a novel and the third listed EGFR-TKIs, which could exert a good anti-tumor efficacy on NSCLC,especially in the re-treatment of advanced NSCLC." (PMID 28430623, 2017). "In selected cases where material and assays were available, it was possible to confirm the new variants identified in plasma, thus confirming that they are not sequence artifact but rather reflect an higher heterogeneity of EGFR mutant tumors as compared to what revealed by tumor tissue analyses." (PMID 27448974, 2016). "Somatic mutation analyses of FLCN, EGFR, and KRAS were also done in microdissected neoplasms." (PMID 26974543, 2016). "In particular, mice with EGFR-driven tumours show elevated PD-L1 expression." (PMID 27433281, 2016). "In addition to cytomorphological analysis, gene expression of tumor associated genes (Cytokeratin-18, Cytokeratin-19, Cytokeratin-20, Cytokeratin-7, EPCAM, MUC1, HER2, EGFR) and of leukocyte markers (e.g. CD45, CD68) was tested in enriched CTC fractions." (PMID 25862542, 2016). "The presence of IL-17E in the TNBC tumor microenvironment may pre-activate the EGFR via Src/PYK2 crosstalk, thus resulting in enhanced sensitivity to EGF and potentially other EGFR ligands." (PMID 27462789, 2016). "His tumour was wild type for EGFR, KRAS and ALK, but did display MET positivity by IHC." (PMID 26883990, 2016). "Interestingly, targeted NGS showed that cells enriched in sphere culture lost their EGFR and NF1 mutations that were expressed in the tumor core biopsy." (PMID 27605047, 2016). "Tumor samples were evaluated for EGFR cytoplasmatic expression by IHC and among the 52 patients categorized as EGFR low-to-moderate, the response rate was 41% for those treated with cisplatin plus cetuximab, compared with 12% for those treated with cisplatin and placebo (p=0.03)." (PMID 27556186, 2016). "Third, the EGFR mutation status was evaluated by using samples from the original lung tumor rather than from the BM lesions, but the potential heterogeneity of tumor tissues was not taken into consideration in this study." (PMID 27486770, 2016).